UCHL1 (ubiquitin C-terminal hydrolase L1)
Diseases named in the same sentence as UCHL1 in open-access papers (continued):
Sharing a sentence is not in itself a finding about the gene and the disease.
Ataxia (12 papers, 2012 to 2025). Ataxia refers to impaired coordination of voluntary muscle movement. "Heterozygous loss‐of‐function variants in UCHL1 lead to a neurodegenerative disease with pyramidal features, ataxia, optic, and peripheral neuropathy." (PMID 39548852, 2025). "Deleterious variants in UCHL1 have been recently linked to optic atrophy, ataxia with subtle hearing loss (auditory neuropathy), demonstrating its importance in maintaining protein homeostasis." (PMID 41191133, 2025). "Autosomal recessive missense variants in Ubiquitin C-terminal hydrolase L1 (UCHL1) are a recognised cause of autosomal recessive spastic paraplegia type 79 (SPG79) which is characterised by early onset cerebellar ataxia, spastic paraplegia and optic atrophy." (PMID 39083076, 2024). "Homozygous or compound heterozygous mutations in the neuronal gene Ubiquitin C-terminal Hydrolase L1 (SPG79/UCHL1) at 4p13 contribute to neurodegenerative phenotypes, with clinical manifestations including cognitive deterioration with neuropathy in the peripheral region and cerebellar ataxia." (PMID 35163618, 2022).
cardiac hypertrophy (12 papers, 2014 to 2024). "REST deficiency up-regulated UCHL1 expression, which then exacerbated cardiac hypertrophy." (PMID 39157454, 2024). "A recent study has reported that UCHL1 is significantly up-regulated in hypertrophic hearts, and positively regulates cardiac hypertrophy through stabilizing epidermal growth factor receptors." (PMID 39157454, 2024). "The positive UCHL1/apoptosis axis is required for spermatogenesis and is involved in suppressing cardiac hypertrophy." (PMID 33919439, 2021). "Knockdown of UCHL1 in cardiomyocytes and mouse hearts rescued cardiac hypertrophy induced by agonist or pressure overload, and overexpression resulted in the opposite effect." (PMID 32656641, 2020). "Overexpression of UCHL1 exacerbates pressure-overload induced cardiac hypertrophy and dysfunction, which can be reversed by systemic administration of the UCHL1 inhibitor LDN-57444 in mice." (PMID 33195472, 2020). "In a cardiac hypertrophy model (both in vitro and in vivo), UCHL1 expression was upregulated." (PMID 33919439, 2021). "The cardiac dysfunction of mice with cardiac hypertrophy induced by TAC was dramatically relieved after treatment with LDN-57444, an inhibitor of UCHL1, indicating that UCHL1 may be employed as a potential drug target for the therapy of cardiac hypertrophy in the future." (PMID 38525836, 2024). "Another hypertrophic factor, Ubiquitin C-terminal hydrolase L1 (UCHL1) is related to fibrosis and has proven to deubiquitinate and stabilize the epidermal growth factor receptor (EGFR), promoting cardiac hypertrophy." (PMID 36860278, 2023). "Downregulation of UCHL1 expression decreases apoptosis and EGFR signaling and suppresses heart remodeling after the onset of cardiac hypertrophy." (PMID 33919439, 2021).
multiple myeloma (10 papers, 2015 to 2025). "For example, pharmacological inhibition of UCHL1 with LDN-57444 induces the G1 phase cell cycle arrest in multiple myeloma." (PMID 41155583, 2025). "To evaluate the nature of UCHL1hi myeloma cases, we plotted UCHL1 levels across 596 myeloma primary specimens and 50 human myeloma cell lines according to TC grouping." (PMID 26513019, 2015). "Targeting UCHL1 in KMS11 and KMM1 myeloma cell lines could suppress the expression of the UCHL1 protein resulting in G1 phase arrest in MM cell lines." (PMID 34257568, 2021). "Finally, the molecule was used for initial probe studies to assess the role of UCHL1 role in proliferation of myeloma cells and migration behavior in small cell lung cancer cells making 34 a new tool to be used in the biological evaluation of UCHL1." (PMID 33668938, 2021). "Based on these data, we conclude that the relapse of myeloma following shRNA depletion of UCH-L1 results from a loss of efficacy of the UCHL1 targeting shRNA, and not due to loss of dependence on UCH-L1." (PMID 26513019, 2015). "In two prior reports we characterized a series of UCHL1 targeting shRNAs and found them to similarly induce cell death in three different UCH-L1 expressing myeloma cell lines, but not in a UCH-L1 negative line." (PMID 26513019, 2015). "The candidate enhancers of HGF and UCHL1 exemplify de novo formed enhancers, i.e., not present at any stage of late B lineage development, while the CCND2 enhancer provides an example of ‘re-commissioned’ super-enhancer, i.e., active in myeloma but not in normal PC." (PMID 34521827, 2021).
colon cancer (9 papers, 2004 to 2024). "Human colon cancer cell lines with chr13q gain were less sensitive to CRISPR/Cas9-mediated knockout of UCHL1." (PMID 38622679, 2024). "The UCHL1 promoter is silenced by methylation in human colon cancer and can be demethylated by specific treatments, inducing expression of Metridia luciferase and EGFP reporter genes." (PMID 31060628, 2019). "However, there is evidence suggests that UCHL1 is an oncogene in some cancers, such as colon cancer." (PMID 25577646, 2015).
hepatocellular carcinoma (9 papers, 2011 to 2025). A malignant tumor that arises from hepatocytes. "Conversely, in hepatocellular carcinoma it was found that overexpression of UCHL1 combated chemoresistance to verapamil and adriamycin and enhanced apoptosis rates." (PMID 40078282, 2025). "A previous study showed that UCHL1 overexpression supported apoptosis in verapamil- and Adriamycin-treated hepatoma cell lines (BEL-7402 and SMMC-7721)." (PMID 36233276, 2022). "Significantly, the mechanisms by which UCHL1 induces chemoresistance in some cancers, such as pediatric high-grade gliomas and hepatoma cells, have been reported previously." (PMID 33718207, 2021).
lung adenocarcinoma (9 papers, 2010 to 2024). A carcinoma that arises from the lung and is characterized by the presence of malignant glandular epithelial cells. "Through executing loss of function tests, we affirmed that silencing of UCHL1 expression significantly inhibited migration and invasion of lung adenocarcinoma cells in vitro." (PMID 35546675, 2022). "Based on cases from the publicly available databases, we further confirmed that high expression of UCHL1 in lung adenocarcinoma was associated with a higher rate of chemoresistance and a lower rate of OS." (PMID 32483437, 2020). "UCHL1 downregulation decreases the proliferation, migration, and invasion of lung adenocarcinoma cells." (PMID 37575253, 2023). "In another study, UCHL1 overexpression improves the early diagnosis and detection rate and provides targeted drug therapy for lung adenocarcinoma." (PMID 36233276, 2022). "The results showed that ACAN, CDKN3, GRIN2A, IL17A, KCNQ2, TIMP1, and UCHL1 were significantly up-regulated in lung adenocarcinoma cells." (PMID 36147496, 2022). "In lung adenocarcinoma, UCHL1 promotes tumor migration, invasion, and metastasis by inhibiting apoptosis and has an important impact on the clinical drug treatment of lung adenocarcinoma." (PMID 35546675, 2022). "Our results indicate that the proliferation, migration, and invasion of lung adenocarcinoma cells are reduced with the silencing of UCHL1 gene, which further explains the carcinogenic role of UCHL1 in tumors." (PMID 35546675, 2022). "The GraphPad Prism7.0 program was performed to compare the relative levels of UCHL1 and Ki-67 between normal and malignant lung adenocarcinoma tissues." (PMID 35546675, 2022). "In order to prove the role of UCHL1 in the metastasis of lung adenocarcinoma, we used the classical scratch and Transwell method to detect the influence of UCHL1 on the migration and invasion of lung adenocarcinoma cells." (PMID 35546675, 2022). "The results showed that the expression of UCHL1 protein in lung adenocarcinoma was higher than that in normal tissues." (PMID 35546675, 2022). "Meanwhile, we used a human lung adenocarcinoma TMA for UCHL1 protein expression and revealed that the expression of UCHL1 was lower in the adjacent normal tissues, but higher in the malignant tissues of lung adenocarcinoma patients." (PMID 35546675, 2022). "The results showed that the migration and invasion of lung adenocarcinoma cells were significantly reduced with the silencing of UCHL1." (PMID 35546675, 2022). "In our study, the expression pattern of UCHL1 protein in normal and lung adenocarcinoma tissues was further interpreted." (PMID 35546675, 2022). "In order to test the detection efficiency of UCHL1 for lung adenocarcinoma in this study, we analyzed the detection rate of lung adenocarcinoma in a bioinformatics database combined with common clinical indicators." (PMID 35546675, 2022). "In terms of the detection rate of lung adenocarcinoma indicators, we analyzed the impact of UCHL1 combined with common clinical indicators on the detection rate of lung adenocarcinoma through a bioinformatics database." (PMID 35546675, 2022). "So far, there is a limited understanding of the mechanism of UCHL1 regulation in lung adenocarcinoma, which needs further study." (PMID 35546675, 2022). "The purpose of this study was to investigate the mechanism of UCHL1 in lung adenocarcinoma cells by silencing the UCHL1 gene." (PMID 35546675, 2022). "B The expression of UCHL1 and Ki-67 in normal and malignant lung adenocarcinoma tissues (magnification × 40, × 200) was recorded." (PMID 35546675, 2022). "We analyzed the differential expression of the UCHL1 gene in lung adenocarcinoma and normal lung tissues, and the correlation between the UCHL1 gene and prognosis was also analyzed by the bioinformatics database TCGA." (PMID 35546675, 2022).
lung adenocarcinoma (continued). "In this study, the analysis of UCHL1 protein expression in lung adenocarcinoma proved that obviously higher UCHL1 protein level was discovered in lung adenocarcinoma tissues." (PMID 35546675, 2022). "At the same time, we analyzed the effect of UCHL1 on anti-tumor drug sensitivity of lung adenocarcinoma by a bioinformatics database." (PMID 35546675, 2022). "A Staining for UCHL1 on lung adenocarcinoma tissue microarrays (TMAs) containing 150 pairs of normal and malignant lung adenocarcinoma tissues." (PMID 35546675, 2022). "The results explained that the high expression of UBE2C, UCHL1, TRAIP, TNNT1, TNNI3, and RAC3 were associated with poor overall survival of lung adenocarcinoma patients (p < 0.05)." (PMID 33050659, 2020). "Above all, UCHL1 may be a new marker for the diagnosis of lung adenocarcinoma and provide a new target for the treatment of clinical diseases." (PMID 35546675, 2022). "In terms of the detection rate of lung adenocarcinoma indicators, we discovered UCHL1 could improve the detection rate of clinical lung adenocarcinoma and affect drug sensitivity." (PMID 35546675, 2022). "Furthermore, lung adenocarcinoma cells with silenced UCHL1 showed a higher probability of apoptosis." (PMID 35546675, 2022). "Moreover, UCHL1 expression was positively correlated with poor clinical survival of patients with lung adenocarcinoma." (PMID 35546675, 2022). "Compared with ALK, EGFR, and TTF1, UCHL1 has higher predictive accuracy for lung adenocarcinoma." (PMID 35546675, 2022). "Furthermore, the effect of UCHL1 on apoptosis of lung adenocarcinoma cells has been shown for the first time." (PMID 35546675, 2022). "Our results suggested that UCHL1 may be a target for the diagnosis and treatment of lung adenocarcinoma." (PMID 35546675, 2022). "Thus, our study aimed to investigate the expression level of UCHL1 in lung adenocarcinoma and its regulatory effect on drug sensitivity and detection rate of lung adenocarcinoma." (PMID 35546675, 2022). "In addition, UCHL1 can improve the detection rate of clinical lung adenocarcinoma." (PMID 35546675, 2022). "However, the functional mechanism of UCHL1 is unclear in lung adenocarcinoma progression." (PMID 35546675, 2022). "Moreover, we found that UCHL1 can promote the migration and invasion of tumor cells in the functional gene knockout experiment and has an important impact on the clinical drug treatment of lung adenocarcinoma." (PMID 35546675, 2022). "However, the specific mechanism of UCHL1 in lung adenocarcinoma is still unclear." (PMID 35546675, 2022). "Meanwhile, we detected and analyzed the expression of UCHL1 and Ki-67 protein in a tissue microarray (TMA) containing 150 patients with lung adenocarcinoma by immunohistochemistry (IHC) and clinicopathological characteristics by TCGA database." (PMID 35546675, 2022). "However, the role of UCHL1 remains unclear in lung adenocarcinoma." (PMID 35546675, 2022).
amyotrophic lateral sclerosis (8 papers, 2015 to 2025). Amyotrophic lateral sclerosis (ALS) is a neurodegenerative disease characterized by progressive muscular paralysis reflecting degeneration of motor neurons in the primary motor cortex, corticospinal tracts, brainstem and spinal cord. "Crossing UCHL1-eGFP with hSOD1G93A mice generated hSOD1G93A-UeGFP reporter line of amyotrophic lateral sclerosis, and revealed sensory nervous system defects, especially towards disease end-stage." (PMID 26222784, 2015). "By crossing UCHL1-eGFP to amyotrophic lateral sclerosis (ALS) disease models, we generated ALS mouse models with fluorescently labeled motor neurons." (PMID 32098365, 2020).
breast tumor (8 papers, 2004 to 2024). "UCHL1 is mainly expressed in breast tumor cells, and its expression in basal-type and circulating tumor cells is significantly higher than that in Luminal A/B and HER2 + subtypes." (PMID 38468288, 2024). "Functionally, ectopic expression of UCHL1 suppressed the colony formation and cell proliferation of breast tumor cells through inducing G0/G1cell cycle arrest and apoptosis." (PMID 22279545, 2012). "Ectopic expression of UCHL1 significantly suppressed the colony formation and proliferation of breast tumor cells, through inducing G0/G1 cell cycle arrest and apoptosis." (PMID 22279545, 2012). "To address whether methylation occurs in primary tumors, we analyzed the promoter methylation of UCHL1 in 66 breast tumor samples, 20 breast tumor adjacent tissues, and 28 normal breast tissues using MSP." (PMID 22279545, 2012). "Methylation status of the UCHL1 promoter in primary breast tumors." (PMID 22279545, 2012). "Clinicopathological features and UCHL1 methylation of breast tumors." (PMID 22279545, 2012). "We observed that the rate of positive expression (+) of UCHL1 protein is significantly higher in triple negative breast tumors (34.5%, 10/29) than that in luminal A (4.3%, 2/47), luminal B (4.2%, 2/48) and HER2+ (0%, 0/45) breast tumors." (PMID 32042339, 2020).
Cerebral ischemia (8 papers, 2015 to 2025). Restriction of arterial blood supply to the brain associated with insufficient oxygenation to support the metabolic requirements of the tissue. "Convergent studies have established the pivotal role of ubiquitin C-terminal hydrolase L1 (UCHL1) in axonal preservation and functional recovery following cerebral ischemia, though distinct research groups have elucidated complementary facets of its activity." (PMID 40529211, 2025). "After cerebral ischemia, UCHL1 is deactivated by reactive lipids, which bind to the C152 residue of UCHL1, leading to an impaired ubiquitin‐proteasome pathway." (PMID 38778460, 2024). "Cerebral ischemia generates reactive lipids, such as cyclopentenone prostaglandins (CyPgs), that covalently modify the amino acid cysteine (C152) of UCHL1, reducing its activity and promote ischemic damage." (PMID 34638676, 2021). "This suggests that there may be other undiscovered pathways through which UCHL1 affects neurological disorders, such as cerebral ischemia." (PMID 41036271, 2025). "Thus, we concluded that CEA significantly affects serum CNDP1 and UCHL1 concentrations, and therefore these enzyme concentrations seem to reflect brain ischemia resulting from severe internal carotid artery stenosis in patients undergoing CEA." (PMID 31460820, 2019). "Multiple studies have indicated that UCHL1 could play a part in determining the survival of gray and white matter, alleviating gray and white matter damage, and contributing to motor recovery post-cerebral ischemia." (PMID 41036271, 2025). "UCHL1 may play an important role in maintaining axonal function after cerebral ischemia." (PMID 35203526, 2022). "Furthermore, proteins as HSC70, DRP2, enolase 1, UCHL1, ADK1, and particularly NDKA and even more Rho-GDI, exhibit higher association levels to 4E-BP2 in cerebral cortex and could be considered as biomarkers of resilience to cerebral ischemia." (PMID 34638676, 2021).
dementia (8 papers, 2008 to 2025). Loss of intellectual abilities interfering with an individual's social and occupational functions. "Similarly, reduced overall gene expression of UCHL-1 is associated with the formation of Lewy bodies in patients with dementia and the development of gracile axonal dystrophy and intraneuronal inclusions in mice." (PMID 18671875, 2008). "Higher levels of UCHL1 were previously found in CSF from a small group of AD patients compared with healthy controls, stable MCI, and patients affected by other dementias." (PMID 37454217, 2023). "However, while UCHL1 and FABP3 appeared to be specific for AD, PKM activity increased in both AD and FTD patients, underlining that these two diseases may share alterations of energy metabolism that should be further explored as candidate pathways involved in dementia." (PMID 37454217, 2023).
epilepsy (8 papers, 2012 to 2026). A brain disorder characterized by episodes of abnormally increased neuronal discharge resulting in transient episodes of sensory or motor neurological dysfunction, or psychic dysfunction. "Pre-clinical evidence of epilepsy has shown that in kindled rats with intraperitoneal pentylenetetrazol injections, plasma UCHL-1 levels were increased compared to controls, and levels were proportionally elevated in relation to the number of injections." (PMID 37569895, 2023). "Across both cohorts, neonates with epilepsy had higher concentrations of the pro-inflammatory cytokine IL-1β and the neuronal injury marker UCHL1 compared to those without epilepsy." (PMID 42106818, 2026). "Multiple plasma proteins have been suggested to be epilepsy biomarkers, but many are neuronal proteins associated with non-specific brain injury (tau, GFAP, UCHL1, etc.)." (PMID 39812831, 2025).